GTF3A (general transcription factor IIIA)
Description:
Involved in ribosomal large subunit biogenesis. Binds the approximately 50 base pairs internal control region (ICR) of 5S ribosomal RNA genes. It is required for their RNA polymerase III-dependent transcription and may also maintain the transcription of other genes. Also binds the transcribed 5S RNA's (By similarity).
Synonyms: TFIIIA; AP2
Tractability: PROTAC: ubiquitination databases record sites on it.
Gene: Protein-coding gene on chromosome 13 (27,424,619 to 27,435,823, forward strand). Ensembl gene ENSG00000122034.
Subcellular location: Nucleus
Subcellular location (Human Protein Atlas): Nucleoplasm
Pathways (Reactome):
Gene expression (Transcription): RNA Polymerase III Abortive And Retractive Initiation; RNA Polymerase III Transcription Initiation From Type 1 Promoter
Gene Ontology:
Molecular function: 5S rRNA binding; DNA binding; nucleic acid binding
Biological process: ribosomal large subunit biogenesis; rRNA transcription; transcription by RNA polymerase III
Cellular component: nucleoplasm; nucleus
Genetic constraint (gnomAD): Loss-of-function variants: 12 observed, 8.83 expected, observed/expected ratio (o/e) 1.36, 90% interval 0.85 to 1.89. That is too few expected variants to judge how well the gene tolerates losing a copy. Missense variants: 253 observed, 192.66 expected, observed/expected ratio (o/e) 1.31, 90% interval 1.18 to 1.46. Synonymous variants: 98 observed, 78.49 expected, observed/expected ratio (o/e) 1.25, 90% interval 1.06 to 1.48.
Homologues: Orthologues: chimpanzee GTF3A (99% identical), macaque GTF3A (96% identical), dog GTF3A (84% identical), pig GTF3A (83% identical), rat Gtf3a (79% identical), mouse Gtf3a (78% identical), guinea pig GTF3A (75% identical), rabbit GTF3A (70% identical), tropical clawed frog gtf3a (54% identical), zebrafish gtf3aa (48% identical), zebrafish gtf3ab (38% identical), Drosophila melanogaster CG6654 (21% identical), and 2 more. Paralogues in human: ZNF324 (29% identical), ZNF324B (27% identical), ZNF652 (25% identical), ZBTB47 (24% identical), ZNF513 (23% identical), ZUP1 (19% identical).
Diseases named in the same sentence as GTF3A in open-access papers:
GTF3A is named in the same sentence as 18 diseases in open-access papers, as found by Europe PMC text mining. Sharing a sentence is not in itself a finding about the gene and the disease. The quoted sentences say what the papers report.
colorectal cancer (3 papers, 2019 to 2022). A primary or metastatic malignant neoplasm that affects the colon or rectum. "GTF3A is considered to be associated with the migration of different types of cancer, and in colorectal cancer, high GTF3A and GTF3B expression seems to be associated with poor prognosis." (PMID 36698419, 2022). "Collectively, our study declares that GTF3A was overexpressed in cancer tissues and cell lines, particularly colorectal cancer, and it could possibly step in as a potential prognostic biomarker." (PMID 33925358, 2021). "The general transcription factor III (GTF3) family, comprising GTF3A, GTF3B, GTF3C1, and GTFC2, were stated to be linked with the expansion of different types of cancers; however, their messenger (m)RNA expressions and prognostic values in colorectal cancer need to be further investigated." (PMID 33925358, 2021). "Clinically, high GTF3A and GTF3B expressions were significantly correlated with poor prognoses in colorectal cancer patients." (PMID 33925358, 2021).
leukemia (2 papers, 2021). A malignant (clonal) hematologic disorder, involving hematopoietic stem cells and characterized by the presence of primitive or atypical myeloid or lymphoid cells in the bone marrow and the blood. "Among all GTF3 members, GTF3A was particularly highly expressed in CRC compared to normal tissues, whereas GTF3B, GTF3C1, and GTF3C2 had low expression levels in other types of cancers such as brain and central nervous system cancers, esophageal cancer, and leukemia." (PMID 33925358, 2021).
acute myeloid leukemia (1 paper, 2008). Acute myeloid leukemia (AML) is a group of neoplasms arising from precursor cells committed to the myeloid cell-line differentiation. "A recent study identified GTF3A as down-regulated in Down syndrome leukocytes in comparison to normal controls, which might implicate GTF3A dysfunction in Down syndrome-associated acute myeloid leukemia." (PMID 18179710, 2008).
cervical carcinoma (1 paper, 2015). A carcinoma arising from either the exocervical squamous epithelium or the endocervical glandular epithelium. "PDCD6 gene expression was higher in cells sensitive to L-OHP, whileexpression of PDS5B, UBL3, MTIF3,XPO4, CASC8, and GTF3A was lower.UBL3 was identified as one of seven genes that predict relapse andsurvival in early-stage cervical carcinoma patients." (PMID 26678268, 2015).
lymphoma (1 paper, 2008). A malignant (clonal) proliferation of B- lymphocytes or T- lymphocytes which involves the lymph nodes, bone marrow and/or extranodal sites. "There is no published information regarding the role of GTF3A in lymphoma, therefore further analysis is required to determine the significance of GTF3A in HL and ALCL." (PMID 18179710, 2008).
tumor (2 papers, 2021 to 2022). "Based on GEPIA analysis, the expression level of GTF3A in CRC was higher in tumor tissue relative to normal tissues." (PMID 33925358, 2021). "A possible explanation for this conflict may be that GTF3A acts differently in different stages of tumor cells." (PMID 33925358, 2021). "Conversely, some well-known factors related to tumor growth promotion, such as HMGA1, GTF3A, PHF19, CENPX, and MBD2, were upregulated." (PMID 35935940, 2022).
GTF3A also shares sentences with these, for which no sentence is quoted: infection (5 papers); cancer (3); colon carcinoma (2); viral infection (2); celiac disease (1); central nervous system cancer (1); colon adenocarcinoma (1); Down syndrome (1); esophageal cancer (1); mastitis (1); melanoma (1); Obesity (1).